PEG3 (paternally expressed 3)
Diseases named in the same sentence as PEG3 in open-access papers (continued):
Sharing a sentence is not in itself a finding about the gene and the disease.
transient neonatal diabetes mellitus (2 papers, 2013 to 2024). Transient neonatal diabetes mellitus (TNDM) is a genetically heterogeneous form of neonatal diabetes (NDM) characterized by hyperglycemia presenting in the neonatal period that remits during infancy but recurs in later life in most patients. "Approximately half of transient neonatal diabetes mellitus (TNDM) patients with methylation disturbance at PLAGL1 have biallelic pathogenic variants in ZFP57, and have MLID involving LOM at PLAGL1, GRB10, and PEG3." (PMID 39090763, 2024).
cervical cancer (1 paper, 2018). A primary or metastatic malignant neoplasm involving the cervix. "Notably, PEG3, SPON1, BTD and RPLP2 passed the defined threshold of FDR <0.25, indicating the potential of these genes in showing their significances in cervical cancer." (PMID 30065881, 2018).
colorectal cancer (1 paper, 2020). A primary or metastatic malignant neoplasm that affects the colon or rectum. "Among 98 Chinese patients with colorectal cancer, PEG3 showed a mutation frequency of 10.6%." (PMID 32729618, 2020).
ductal breast carcinoma (1 paper, 2012). "This database was specified to query individual published microarray analyses as well as to produce a summary statistic across each distinctive gene expression study for PEG3 mRNA levels detected in various ductal breast carcinoma samples." (PMID 23029096, 2012).
growth disorders (1 paper, 2018). "Dysregulation of imprinting at Peg3 has been associated with growth disorders." (PMID 29698523, 2018).
melanoma (1 paper, 2022). A malignant, usually aggressive tumor composed of atypical, neoplastic melanocytes. "By performing survival analysis based on gene pair mutation, we observed that the mutation of nine gene pairs, such as “SERPINB3|RELN”, “KAT6B|RELN”, and “SERPINB3|PEG3”, were significantly correlated with patient survival in all four independent melanoma datasets (log-rank test p-value < 0.05)." (PMID 36139377, 2022).
ovarian dysfunction (1 paper, 2025). The inability of the ovaries to function. "Changes in the methylation levels of imprinted genes H19 and Peg3 may also lead to ovarian dysfunction." (PMID 41465099, 2025).
Stillbirth (1 paper, 2010). Death of the fetus in utero after at least 22 weeks of gestation. "Interestingly, aberrant methylation of the PEG3 gene (resulting in altered expression) has been observed in cases involving stillbirths and aborted foetuses in humans and aborted cloned bovine embryos, suggesting that this gene has an important role in embryo and foetal viability and survival." (PMID 20942903, 2010).
thymic lymphoma (1 paper, 2017). "The epigenetic instability at imprinting control regions was also seen in our previous report on the infiltrative thymic lymphoma, which were isolated from mice using a different breeding scheme involving a conditional knockout construct for Peg3 that was bred into the KrasG12D model." (PMID 28855972, 2017).
triple-negative breast carcinoma (1 paper, 2017). An invasive breast carcinoma which is negative for expression of estrogen receptor (ER), progesterone receptor (PR), and human epidermal growth factor receptor 2 (HER2). "As decorin induces rapid Thrombospondin 1 (TSP-1) secretion in triple negative breast carcinoma cells, we hypothesized that the decorin-inducible Peg3 could be directly involved in stimulating the release and potential synthesis of TSP-1." (PMID 28174297, 2017).
cancer (31 papers, 2010 to 2025). A tumor composed of atypical neoplastic, often pleomorphic cells that invade other tissues. "Further, the expression of the transcription factor “PEG3” is known to be associated with the processes of cancer aggressiveness and angiogenesis." (PMID 28148240, 2017). "PEG3 encodes a tumor suppressor and was downregulated in several cancer types." (PMID 28427185, 2017). "Among the upregulated genes were those linked to cancer formation (e.g., STOX1, PEG3, XIAP) and immune cell recruitment (e.g., CCL28, VIM), suggesting a shift towards increased cellular proliferation and remodelling of the immune microenvironment." (PMID 40683913, 2025). "The regulatory network analysis showed the association of some important hub proteins like GSK3B, NUMB, PEG3, ITGA2 and DLG2 with cancer-associated pathways." (PMID 28587194, 2017). "In contrast, lower expression of the downregulated genes (such as SCARA5, MYOM1, NKAPL, PEG3, USP2, SLC5A7 and HMGCLL1) in various cancers is associated with poor clinical outcomes in cancer." (PMID 28427185, 2017). "Although the actions of EGCG involve multiple targets/pathways, further analysis by mining the existing genomic datasets revealed that the upregulations of Myb and Peg3 are likely the key anti-cancer events of EGCG in vivo." (PMID 27461468, 2016). "The growth-inhibitory imprinted gene Peg3 is not expressed by C26 cells, which is highly relevant since loss of Peg3 expression through promoter methylation, loss of heterozygosity and other mechanisms may stimulate clonogenic growth and contribute to the pathogenesis of a number of cancers." (PMID 20615237, 2010). "Given that the PEG3 promoter resides within a CpG-rich region that is differentially methylated in cancers, we asked whether increased expression of PEG3 in TGCTs could be due to loss of its promoter methylation." (PMID 28471449, 2017). "Under the assumption that, if a gene mediates EGCG’s cancer inhibition, its expression level change caused by EGCG should be opposite to what occurred in the carcinogenesis, we identified Myb and Peg3 as the primary putative genes involved in the cancer inhibitory activity." (PMID 27461468, 2016). "Loss of imprinted tumor suppressor function for NDN, DIRAS3 and PEG3 might permit growth of cancer cells in culture." (PMID 26689988, 2016). "This suggests that Myb might play a much more critical role than Peg3 in mediating the anti-cancer activity of EGCG." (PMID 27461468, 2016). "PEG3 encodes a Kruppel-type zinc-finger protein which regulates the tumour necrosis factor (TNF) response, of which dysregulation is commonly implicated in cancer [OMIM 601483]." (PMID 26347357, 2015). "In summary, a series of DNA methylation surveys revealed that a relatively large fraction of imprinted genes are epigenetically affected in human cancers, and also that this epigenetic instability is particularly pronounced in a subset of imprinted genes, such as PEG3, IGF2, DLK1, MEST and GNAS." (PMID 26338779, 2015). "At the gene level, FDCSP (cancer cell migration and invasion), KIR2DL3 (immune response), SLC30A10 (antiapoptotic), MAB21L2, PCDH9 (cell adhesion), PEG3 (cell proliferation) were found to be highly expressed in the Lymph-node (LN)-positive samples." (PMID 37377901, 2023). "We identified consistently upregulated genes (such as E2F1, EZH2, FOXM1, MYBL2, PLK1, TTK, AURKA/B and BUB1) and consistently downregulated genes (such as SCARA5, MYOM1, NKAPL, PEG3, USP2, SLC5A7 and HMGCLL1) across various cancers." (PMID 28427185, 2017). "Four of these genes (PCGME1, PEG3, EPHA3, and EFNB2) are of particular interest as they are known to modulate cancer cell proliferation and/or survival." (PMID 28035996, 2016). "First, we targeted the following loci given the initial observation from TCGA: five imprinted domains (PEG3, H19/IGF2, DLK1/GTL2, MEST, GNAS) and four cancer genes (APC, MLL3, MGMT, ELF3)." (PMID 26338779, 2015).
cancer (continued). "Among the ten genes, five of the TSGs (ATM, APC, BRCA2, NF1, and PTEN) were annotated with positive effects on apoptosis; the other three TSGs (PEG3, SPARC, and RPS6KA2) were also reported to increase apoptosis in sporadic epithelial OVC or other types of cancer." (PMID 22952919, 2012). "Expression of Peg3, a growth-inhibitory imprinted gene which is frequently down-regulated in cancer, was absent (data not shown)." (PMID 20615237, 2010).
tumor (31 papers, 2004 to 2025). "We found that PEG3 expression was positively associated with the largest tumor size (unpaired Student's t-test, p = 0.044), vascular thrombosis, differentiation, and UICC stage (Chi-square test, p = 0.038)." (PMID 36451866, 2022). "Early FDIM showed upregulation of genes linked to tumour initiation, immune recruitment, and motility (e.g., STOX1, PEG3, XIAP, MCAM, VIM)." (PMID 40683913, 2025). "Initially characterized as a tumor suppressor, we discovered that Peg3 acts as a nexus for decorin- (and other PGs)-mediated autophagy." (PMID 35159071, 2022). "Taken together, these results indicate that knockdown of Peg3 significantly block hyperactive mTOR-mediated HCC tumor progress and migration." (PMID 36451866, 2022). "Peg3 was identified from a subset of differentially expressed genes exclusively within the murine tumor stroma of triple negative orthotopic tumor xenografts treated systemically with human recombinant decorin." (PMID 35159071, 2022). "Namely, DCN induces the expression of paternally expressed gene 3 (Peg3), an imprinted tumor suppressor gene, and Peg3 relocates into autophagosomes." (PMID 26697491, 2015). "An additional decorin-induced target classified as a tumor suppressor gene within the stroma, was Peg3 (paternally expressed gene 3, 2.49-folds, P = 0.0078) and it encodes a zinc finger transcription factor (Cys2His2 variety) of the Krüpple-type family." (PMID 23029096, 2012). "Systemic treatment with decorin resulted in an induction of Peg3 as well as Bmp2k and Zc3hav1 within the tumor stroma as visualized via immunofluorescence and quantified using three-dimensional surface plots of the fluorescent signal." (PMID 23029096, 2012). "Analysis of these stromal genes in context of the co-culture via qPCR revealed a recapitulation of the expression patterns of Peg3, Bmp2k, and Zc3hav1 (P<0.001), the same stromal genes verified as induced by decorin within the tumor xenografts." (PMID 23029096, 2012). "For instance, hypermethylation at the ICR of the H19/Igf2 domain can potentially result in complete repression of H19 and bi-allelic expression of Igf2, a known oncogene, whereas hypermethylation at the ICR of the Peg3 domain can potentially result in repression of Peg3, a putative tumor suppressor." (PMID 28855972, 2017). "Thus, these in vivo data provides further proof that decorin significantly affects the tumor microenvironment via induction of Peg3, Bmp2k and Zc3hav1 at the protein and transcriptional levels as suggested by the mixed microarray data." (PMID 23029096, 2012). "Moreover, METTL3 also upregulates the level of miR-1246 which reduces the expression of the tumor suppressor PEG3 to promote the development of lung adenocarcinoma; In addition, METTL3 can also promote tumor proliferation, EMT, invasion, and migration by down-regulating miRNAs, such as: miR-1915-3p." (PMID 35784761, 2022). "Among the top 100 deregulated genes, Wnt-associated genes such as LGR5, DKK1, and NKD1, as well as the HB-related genes DUSP9, DLK1, PEG3, PEG10, IGF2BP1, and IGF2BP2 were consistently upregulated in tumor samples." (PMID 40968384, 2025).
tumor (continued). "Consistently, PEG3 was higher expression in HCC tumor tissues (paired Student's t-test, GSE14520: p < 0.0001, PXD006512: p = 0.0036) than in non-tumor tissues." (PMID 36451866, 2022). "Downregulated tumour suppressors DIRAS3, DLEC1 and PEG3 (all, P < 0.001) were frequently observed in the immune group." (PMID 33522069, 2021). "For example, PYY, CD177, PEG3, and FAM83D, were observed in more than 11 normal samples, while less than 3 were observed in tumor samples." (PMID 30538721, 2018). "Several tumour suppressor genes (BAI3, PEG3, PRDM2, RB1CC1) along with the natural killer receptor KLRC1 were also down regulated in BAT." (PMID 23472076, 2013). "We found that knockdown of Peg3 significantly attenuated mTOR hyperactive HCC tumorigenesis and metastasis using subcutaneous xenograft mouse model and tail-vein intravenous injection in vivo, indicated by tumor volume, tumor weight, and lung metastasis." (PMID 36451866, 2022). "While our literature research has not found any role of Myl4 in carcinogenesis, Peg3 has been reported to act like a tumor suppressor gene." (PMID 27461468, 2016). "Furthermore, PEG3 mutation was significantly associated with high TMB and inferior prognosis, and the associations were independent of multiple confounding factors including age, tumor stage and mutations of BRCA1, BRCA2 and POLE." (PMID 32729618, 2020). "Samples where RFLPs were present in the lymphocyte DNA sample but absent or with an altered ratio in the tumor sample were considered to exhibit LOH in the regions of 8 imprinted genes (H19, IGF2, KCNQ1, LIT1, GTL2, PEG1, PEG3 and NDN)." (PMID 22443985, 2012). "Firstly, the PEG3 promoter is activated specifically in tumor cells by the PEA3/AP-1 transcription factors, regulating the specific expression of FTH1 at the transcriptional level, thereby ensuring FTH1 expression is restricted to tumor tissues and absent in normal tissues." (PMID 40723232, 2025).
metabolic disease (2 papers, 2017 to 2021). A congenital disorder (due to inherited enzyme abnormality) or acquired (due to failure of a metabolically important organ) disorder resulting from an abnormal metabolic process. "In agreement with the high expression of Peg3 in the brain and its role in development, Peg3−/− mice display abnormal behavior and metabolic disorders." (PMID 28174297, 2017).
PEG3 also shares sentences with these, for which no sentence is quoted: embryonal cancers (2 papers); infertile (2); oligodendroglioma (2); acute lymphoblastic leukemia (1); astrocytoma (1); autism (1); cavernomas (1); endometrial cancer (1); esophageal cancer (1); Hepatic fibrosis (1); hepatocellular carcinoma (1); hypopituitarism (1); infection (1); invasive ductal breast carcinoma (1); liver (1); male infertility (1); mood disorder (1); myopathies (1); neurological disease (1); osteosarcoma (1); ovarian tumor (1); Parkinson disease (1); Prader-Willi syndrome (1); squamous cell carcinoma (1); testicular tumors (1); type 1 diabetes (1); Wilms tumor (1).